MIR4681 (microRNA 4681)
Synonyms: hsa-mir-4681
Gene: MicroRNA gene on chromosome 10 (119,377,972 to 119,378,043, forward strand). Ensembl gene ENSG00000265719.
Homologues: Orthologues: chimpanzee MIR4681 (100% identical).